MPHOSPH10 (M-phase phosphoprotein 10)
Description:
Component of the 60-80S U3 small nucleolar ribonucleoprotein (U3 snoRNP). Required for the early cleavages during pre-18S ribosomal RNA processing. Part of the small subunit (SSU) processome, first precursor of the small eukaryotic ribosomal subunit. During the assembly of the SSU processome in the nucleolus, many ribosome biogenesis factors, an RNA chaperone and ribosomal proteins associate with the nascent pre-rRNA and work in concert to generate RNA folding, modifications, rearrangements and cleavage as well as targeted degradation of pre-ribosomal RNA by the RNA exosome.
Synonyms: MPP10; MPP10P; CT90; PPP1R106
Tractability: Small molecule: a structure with a bound ligand is known. PROTAC: UniProt records ubiquitination sites on it; ubiquitination databases record sites on it; its protein half-life has been measured.
Gene: Protein-coding gene on chromosome 2 (71,130,310 to 71,150,101, forward strand). Ensembl gene ENSG00000124383.
Subcellular location: Nucleus, nucleolus; Chromosome
Subcellular location (Human Protein Atlas): Nucleoli; Nucleoli rim; Mitotic chromosome
Pathways (Reactome):
Metabolism of RNA: Major pathway of rRNA processing in the nucleolus and cytosol; rRNA modification in the nucleus and cytosol
Gene Ontology:
Molecular function: protein binding; RNA binding
Biological process: ribosomal small subunit biogenesis; maturation of SSU-rRNA; RNA processing; RNA splicing; RNA splicing, via transesterification reactions; rRNA processing
Cellular component: chromosome; Mpp10 complex; nucleolus; small-subunit processome; nucleoplasm; sno(s)RNA-containing ribonucleoprotein complex; nucleus
Genetic constraint (gnomAD): Loss-of-function variants: 25 observed, 57.17 expected, observed/expected ratio (o/e) 0.44, 90% interval 0.32 to 0.61. The upper end of that interval is the gene's LOEUF score, 0.61, which puts it in group 2 of 6, group 1 being the genes least tolerant of losing a copy. Missense variants: 623 observed, 676.41 expected, observed/expected ratio (o/e) 0.92, 90% interval 0.86 to 0.98. Synonymous variants: 217 observed, 233.4 expected, observed/expected ratio (o/e) 0.93, 90% interval 0.83 to 1.04.
Homologues: Orthologues: chimpanzee MPHOSPH10 (99% identical), macaque MPHOSPH10 (96% identical), dog MPHOSPH10 (86% identical), pig MPHOSPH10 (86% identical), guinea pig MPHOSPH10 (85% identical), rabbit MPHOSPH10 (82% identical), mouse Mphosph10 (82% identical), rat Mphosph10 (80% identical), tropical clawed frog mphosph10 (59% identical), zebrafish mphosph10 (55% identical), Drosophila melanogaster CG13097 (37% identical), Caenorhabditis elegans Y75B8A.7 (32% identical).
Diseases named in the same sentence as MPHOSPH10 in open-access papers:
MPHOSPH10 is named in the same sentence as 7 diseases in open-access papers, as found by Europe PMC text mining. Sharing a sentence is not in itself a finding about the gene and the disease. The quoted sentences say what the papers report.
breast carcinoma (1 paper, 2025). "While PGK1 is a well-characterized glycolytic enzyme with established links to tumor metabolism and hypoxia responses, MPHOSPH10 and MAP2K6 have received comparatively less attention in breast cancer." (PMID 40308601, 2025).
Parkinson disease (1 paper, 2025). A progressive degenerative disorder of the central nervous system characterized by loss of dopamine producing neurons in the substantia nigra and the presence of Lewy bodies in the substantia nigra and locus coeruleus. "MCEE encodes methionine-ethionine carboxy-lyase, essential for sulfur metabolism, while MPHOSPH10 encodes M-phase phosphoprotein 10, implicated in ribosome biogenesis and associated with Parkinson’s disease." (PMID 39796173, 2025).
tumor (4 papers, 2010 to 2025). "M-phase phosphoprotein 10 (MPHOSPH10) belonged to categories of cellular physiologic response and signal transduction, however, its role in tumor progress has still been little studied." (PMID 38098990, 2023).
cancer (1 paper, 2023). A tumor composed of atypical neoplastic, often pleomorphic cells that invade other tissues.
MPHOSPH10 also shares sentences with these, for which no sentence is quoted: cardiomyopathy (1 paper); colorectal cancer (1); hepatocellular carcinoma (1).